LEP (leptin)
Diseases named in the same sentence as LEP in open-access papers (continued):
Sharing a sentence is not in itself a finding about the gene and the disease.
tumor (continued). "However, leptin’s effects on regulating tumor progression as well as its prognostic significance in ccRCC have not yet been addressed." (PMID 33804101, 2021). "They demonstrated that the T cell function in tumor-bearing mice enhances antitumor response compared with an oncolytic control by designing an oncolytic virus to express leptin, as well as promoting memory responses in the oncolytic virus-induced immune infiltrate." (PMID 34202969, 2021). "Lastly, higher circulating leptin concentrations and/or elevated expression of leptin receptors in tumours may be poor prognostic factors." (PMID 34684349, 2021). "Leptin was found to stimulate processes favorable to tumor growth, its migration, and invasion." (PMID 34202922, 2021). "Therefore, the hyperactive leptin signaling network influences the BC through direct effects on tumor cells or indirect impacts on different components of the TME." (PMID 34350120, 2021). "Leptin was suggested to be a prognostic factor in CRC after analyzing survival distributions by using clinicopathological variables (tumor size, lymphovascular invasion, distant metastasis, local recurrence, and tumor relapse) in positive leptin immunostaining CRC." (PMID 34202969, 2021). "Furthermore, several studies suggest that leptin and ObR are overexpressed in tumor tissues, due to hypoxia and/or as a response to insulin, IgF-1 and/or to estradiol." (PMID 33644151, 2021). "Leptin could also drive the tumor to escape from immune attacks by enhancing fatty acid oxidation and tumor resistance to NK cell lysis via PGC-1 activation, thus showing a therapeutic clue for BC by blocking leptin." (PMID 34350120, 2021). "Interestingly, our data showed that LEP methylation profiles were mainly correlated with histological subtype (p = 0.001), tumor site (p = 0.04), menopausal status (p = 0.09), and patients’ age (p = 0.06)." (PMID 34884678, 2021). "Conversely, others have examined whether increased leptin activity could potentially augment or restore T cell function in the context of anti-tumor immunity." (PMID 33927722, 2021). "Furthermore, in PANC-1 tumor cells, leptin induces MMP13 expression and stimulates migration and invasion." (PMID 33670492, 2021). "Leptin produced in adipose tissue can directly affect tumor development through its receptor (ObR)." (PMID 34485124, 2021). "Finally, we verified the contributions of autophagy to leptin‐induced alterations in lipid metabolism in a mouse model of xenograft tumor." (PMID 33226729, 2021). "Also higher serum ObR levels were correlated with smaller tumor size (p = 0.0118), suggesting that ObR shedding occurs in small tumors, modulating the serum levels of free leptin." (PMID 33644151, 2021). "Interestingly, the pro-carcinogenic effect of leptin is enhanced by its autocrine actions in tumor cells." (PMID 33864589, 2021). "Leptin is the signal amplifier of estrogen in tumor epithelial cells." (PMID 34485124, 2021). "Furthermore, in one study, the leptin levels of the advanced tumor group were higher than that of the early group." (PMID 35027962, 2021). "Leptin can directly remodel the TME by inducing metabolic changes in tumor cells and recruiting immune cells such as macrophages, CD8+ T cells, and myeloid-derived suppressor cells (MDSCs), which are capable of producing pro-inflammatory cytokines to maintain angiogenesis and tumor growth." (PMID 34350120, 2021). "However, it is worth noting that although adiponectin is also secreted by adipocytes, it has an anti-tumor effect, and can cross-talk with other adipokines (such as leptin and estrogen) and insulin to play an anti-tumor effect together." (PMID 34485124, 2021). "In addition, the susceptibility of tumor cells to the NK cytotoxic action was found to be reduced by CAA-derived IL-6 and leptin that activate the JAK/STAT3 signaling axis in tumor cells." (PMID 33917351, 2021). "Stimulation of leptin may modulate several types of miRNAs, both oncogenic and tumor suppressor miRs." (PMID 33482868, 2021).
tumor (continued). "Leptin could drive the tumor to escape from immune attacks by enhancing fatty acid oxidation and tumor resistance to NK cell lysis via PGC-1 activation." (PMID 34350120, 2021). "The one with the top consistency score is shown, and it is also noted that leptin might promote tumor cell invasion." (PMID 33804101, 2021). "Furthermore, the tumor inflammatory mononuclear cells revealed to be positive for leptin and ObR immunostaining, with a higher proteins expression in macrophages." (PMID 33644151, 2021). "Interestingly, leptin has been reported to be a mediator in the interaction between tumor cells and CAFs." (PMID 33535537, 2021). "Furthermore, leptin is well known to play a protumoral role, since it promotes angiogenesis, the proliferation, and survival of tumor cells, as well as the inhibition of apoptosis, leading to progression and metastasis." (PMID 34202969, 2021). "Increased CAA-released IL-6 and leptin are essential tumour growth enhancers." (PMID 34561446, 2021). "Therefore, the leptin/ObR axis has been widely studied as a target for an adjuvant therapy, not only in ER-positive tumor status, but also in triple-negative tumors, in which the lack of hormonal receptors reduces the therapeutic options." (PMID 33644151, 2021). "CAAs secrete more chemokine (C–C motif) ligand 2 (CCL2), CCL5, interleukin-1β (IL-1β), IL-6, TNF-α, vascular endothelial growth factor (VEGF) and leptin, etc., which could facilitate the invasion of the tumor and immune escape." (PMID 33413697, 2021). "Encouraged by our in vitro findings we investigated whether leptin exposure impacts tamoxifen-mediated tumor inhibition." (PMID 34389732, 2021). "Leptin signaling through the leptin receptor also activates angiogenesis and might be an important mediator between the tumor and its microenvironment." (PMID 34210055, 2021). "In breast cancer, leptin can induce stemness via JAK/STAT3 regulated fatty acid β-oxidation; augment invasion and metastasis by stimulating macrophage associated IL18 activating NFκB signaling in TAMs and PI3K/Akt signaling in tumor cells." (PMID 33450975, 2021). "In contrast, cats with luminal A showed elevated serum leptin levels, indicating that ER overexpression in the tumor may promotes leptin expression." (PMID 33644151, 2021). "Using 1010 matched case-control pairs within the NSHDS, we investigated circulating levels of insulin, C-peptide, adiponectin, and leptin in relation to the risk of CRC, and molecular subtypes of CRC defined by KRAS and BRAF mutation status and MSI status in the tumor." (PMID 32210264, 2020). "Moreover, leptin contributed to enhanced crosstalk between AnaR cells and macrophages within the tumor microenvironment." (PMID 32260113, 2020). "The expression of leptin and/or Ob-R by tumour tissue indicates aggressive behaviour." (PMID 32033341, 2020). "Research on leptin has shown that it not only plays a key role in metabolism, but also mediates tumor development by enhancing tumor angiogenesis, promoting cell proliferation, migration, invasion, and inhibiting tumor cell apoptosis." (PMID 33256658, 2020). "Serum LEP level had negatively correlated with both tumor grade and tumor size in HCC patients.." (PMID 33369452, 2020). "Besides, adipokines, such as leptin, were able to weaken the anti-tumor effect of hormonal tamoxifen therapy." (PMID 32787888, 2020). "In addition, other biological functions have been described for leptin such as regulation of the immune system and reproductive system, or the induction tumor." (PMID 33334030, 2020). "However, in the obese individuals adiponectin levels are low and that in combination with high leptin levels correlates with larger tumors and higher tumor grade." (PMID 33490070, 2020).
tumor (continued). "The immunohistochemical study revealed that the expression of leptin by tumor and stromal cells of squamous cell carcinoma may contribute to its progression by promoting angiogenesis with subsequently acquiring large tumor size and then advanced stage." (PMID 33008429, 2020). "Additionally, leptin secreted by BMAs reacts with LepR on tumor cells and contributes to tumor progression." (PMID 32674405, 2020). "In addition, we also found that leptin promotes tumor cell growth, which is significant in other control and experimental groups in the time-course cell proliferation assay." (PMID 33255835, 2020). "In the last years, the role of leptin as a mediator of the tumor–stroma interaction has been described but how the lack of its receptor may orchestrate TME is still not completely elucidated." (PMID 32727138, 2020). "The neutralization of leptin in obese mice potentiated the response to AdTrail/CpG immunotherapy leading to increased dendritic cell function and intratumoral T-cell accumulation, resulting in decreased tumor growth." (PMID 33604295, 2020). "Serum LEP level had negatively correlated with both tumor grade and size in HCC patients." (PMID 33369452, 2020). "Leptin was described to have a pro-tumorigenic role modulating the tumor immune microenvironment." (PMID 32120856, 2020). "A first potential target in tumor–stroma interactions is the adipokine leptin." (PMID 33006013, 2020). "In addition, leptin levels are also higher in obese individuals than those of normal weight, which related to tumor cell proliferation." (PMID 32600328, 2020). "Leptin and leptin receptor are found in epithelial cancer cells and they are linked to tumour growth, cell death impairments and angiogenesis induction via increased FGF-2 and VEGF expression, moreover leptin has been shown to be related to chemotherapy responsiveness." (PMID 33371214, 2020). "Of note, leptin is able to shape the tumor microenvironment by inducing multiple concurrent events, for example, a promotion of angiogenesis and a sustained recruitment of monocytes and macrophages, which in turn secrete VEGF (vascular endothelial growth factor) and proinflammatory cytokines." (PMID 32260113, 2020). "Serum LEP level in patients with HCC was negatively correlated with both tumor size and grade." (PMID 33369452, 2020). "The study revealed an impact of physiological concentrations of leptin on the filopodia length and of the co-localization of cofilin and F-actin, suggesting an increased motility of NK cells and a possible support of immune defense against tumor cells." (PMID 32231659, 2020). "An increase in leptin, estrogen receptor alpha (ERα) expression, and aromatase activity has been described in obese subjects in coculture with breast cancer, whose specific block reverted tumor progression and metastasis." (PMID 32478073, 2020). "Mice living in the enriched housing environment showed less tumor growth and more frequent remission in melanoma and colorectal cancer, caused by elevated serum brain-derived neurotrophic factor (BDNF) and markedly lower leptin concentrations." (PMID 33117814, 2020). "Besides, miR-141 and miR-146b-5p were two important tumor suppressor miRNAs in BC, and mediated the p16-negative regulation of leptin in adipocytes." (PMID 32787888, 2020). "In order to test whether leptin signaling could be a therapeutic target for treatment of tumor-induced muscle wasting, these two chemical inhibitors were employed." (PMID 30718259, 2019). "Furthermore, it has been shown that leptin has pro-angiogenic effects while adiponectin can induce apoptosis of tumor cells." (PMID 31534630, 2019). "Indeed, leptin exposure increased tumor volume and doubled tumor size after 13 weeks compared to estradiol treatment." (PMID 30634494, 2019).
tumor (continued). "Thus, the previous studies showed that a proportion of PTC tumors express leptin and OBRs, and their expression is associated with aggressive PTC tumor behaviors, poorer disease-free survival, disease persistence, and recurrence." (PMID 31109060, 2019). "Studies have suggested that a leptin-enriched microenvironment promotes tumor cells." (PMID 31119158, 2019). "Leptin can directly remodel the tumor microenvironment by inducing metabolic changes in tumor cells and recruiting immune cells such as monocytes, macrophages and myeloid-derived suppressor cells (MDSCs) able to produce proinflammatory cytokines that sustain angiogenesis and tumor growth." (PMID 31616626, 2019). "In addition, knockdown of leptin in adipose stromal/stem cells isolated from obese patients resulted in reduced tumor growth and numbers of lung and liver metastasis in SCID (severe combined immunodeficiency)/beige mice." (PMID 30634494, 2019). "The immunohistochemical expression of leptin across grades of tumor have been tabulated." (PMID 30803210, 2019). "It is generally accepted that LEP affects tumor cell invasion and progression." (PMID 31671654, 2019). "Adiponectin usually has an anti-tumor behavior, and leptin increases cellular tumorigenicity." (PMID 31534630, 2019). "Our data provide a new view to treat muscle wasting in leptin-secreting hepatic tumors, and perhaps other leptin-producing tumor types, by inhibiting communication from tumor to muscle, which may provide more effective therapeutic targets." (PMID 30718259, 2019). "In addition to increased ROS, other possible mechanisms underlying the beneficial effect of exercise in slowing tumor growth include the reduction in inflammatory mediators such as IFN-gamma and leptin." (PMID 31528182, 2019). "In our study, we explored an important association between serum leptin levels and tumor non-infiltrated lymphocyte function based on the fact that serum levels of leptin were increased in mice fed a high-fat diet." (PMID 31528182, 2019). "There was a marked elevation in the serum levels of leptin in animals fed a high-fat diet (H) compared with those in the control group (N) and a significant reduction induced by continuous exercise in both the tumor-bearing and tumor-free (H) mice." (PMID 31528182, 2019). "Recently, the involvement of leptin in tumor progression is being explored." (PMID 30803210, 2019). "Interestingly, we found the upregulation of leptin in human patients with various tumor types, further suggesting that leptin is involved in HCC development in humans, as previously reviewed." (PMID 30718259, 2019). "It is well documented that leptin stimulates tumor cell growth and invasion." (PMID 30627158, 2018). "Both leptin and adiponectin exert dose-related effects on tumor cells." (PMID 30013512, 2018). "NILCO could represent the integration of developmental, pro-inflammatory, and pro-angiogenic events critical for leptin-induced cell proliferation/migration and tumor angiogenesis." (PMID 30004402, 2018). "What is more, leptin can also provide a microenvironment for tumor growth." (PMID 31205932, 2018). "Leptin plays a role in promoting the proliferation of tumor cells." (PMID 31205932, 2018). "The investigators suggested that the main tumour regressive effects of CRD might be associated with the decreased production of substances like IGF-1 and leptin." (PMID 30510663, 2018). "More intriguingly, L/A ratio but not serum levels of leptin or adiponectin alone, was positively associated with tumor size." (PMID 30013512, 2018). "Furthermore, they observed significant elevation of mean post-operative serum leptin concentrations in patients who underwent complete tumour resection." (PMID 30510663, 2018). "The effect of leptin on tumor growth is dependent on A/AR or E/ER signaling." (PMID 30013512, 2018). "Second, leptin/LepR pathway could promote the oncogenesis, proliferation and colonization of tumor cells in the bone marrow niche." (PMID 30013512, 2018).
tumor (continued). "Leptin is secreted mainly by the adipose tissue and, in a smaller proportion, by the placenta, stomach, fibroblasts, skeletal muscle, normal and tumor epithelial mammary tissue." (PMID 30404206, 2018). "While this finding needs further evaluation, it might be that IL-6/leptin-induced STAT3 is required earlier in DEN-induced HCC e.g. in tumor initiation or during progression." (PMID 30224299, 2018). "In addition, the mediator of leptin-leptin receptor in triggering tumor proliferation was identified." (PMID 29682217, 2018). "Sex steroids play an indispensable role in the pro-tumor effect of leptin." (PMID 30013512, 2018). "These apparent contradictory observations of tumor growth in vivo could be partly explained by the concurrent local and systemic effects of leptin on adjacent tumor cells and immune cells, respectively." (PMID 28915700, 2017). "Tumor recurrence is less prevailing in high score leptin immunostaining cases." (PMID 29121911, 2017). "Interestingly, co-treatment with tamoxifen prevented leptin-induced tumor growth, indicating that ER signaling is crucial for leptin-induced tumor growth in our in vivo experimental conditions." (PMID 29312618, 2017). "PC cells secreted leptin and expressed the leptin receptor, OB-R, which indicates a leptin autocrine/paracrine signaling loop could also affect tumor progression." (PMID 27999190, 2017). "Moreover, inhibition of leptin signaling via IONP-LPrA2 delayed tumor onset, reduced PC xenograft growth, which correlated to leptin-induced Notch expression and PCSC." (PMID 27999190, 2017). "In human androgen-independent PC-3 and DU145 PCa cell lines, leptin promotes tumor growth." (PMID 28272469, 2017). "Moreover, for the first time, it was found that leptin upregulates Notch in PC, and the specific inhibition of leptin receptor delays tumor onset, decreases tumor growth and PCSC populations." (PMID 27999190, 2017). "Moreover, adipose tissue within the tumor microenvironment actively contributes to tumor growth and metastasis by secreting leptin, adiponectin, free fatty acid (FFA), pro-angiogenic factors, and extracellular matrix constituents." (PMID 28275367, 2017). "LEP is mainly secreted by adipose tissue, and has been suggested to promote tumor growth." (PMID 29312594, 2017). "Leptin signaling pathway is involved in the anti-tumor effects of BMP9 in adipose microenvironment." (PMID 28415788, 2017). "Since both adipokines are secreted by adipocytes and present in the blood, the leptin:adiponectin ratio may be a major factor influencing tumor growth." (PMID 28915700, 2017). "Moreover, pretreatment with tamoxifen, a selective pharmacological inhibitor of ER, was found to suppress leptin-induced tumor growth." (PMID 29312618, 2017). "Leptin is a hormone that regulates adipocyte size and the development of some tumor types." (PMID 29212223, 2017). "Moreover, the connection between hypoxic induction of Hif-α targets, such as VEGF and Leptin, to neoplastic transformation and tumor induction is less clear than the well-documented role of these factors in vascularization supporting tumor growth." (PMID 28192065, 2017). "The relative risk (RR) [95% confidence interval (CI)] was calculated for tumor incidence, and the standardised mean difference (95% CI) was computed for levels of serum insulin-like growth factor-1 (IGF-1), leptin, and adiponectin using a random-effects meta-analysis." (PMID 27653140, 2016). "In addition, it has been observed that knockdown of leptin decreases tumor volume and number of metastases to the lung and liver." (PMID 27293305, 2016). "Additionally, leptin plays critical roles in the regulation of glucose homeostasis and has been implied as an effector of obesity-induced changes in tumor and stroma cells." (PMID 27066006, 2016). "Several studies have revealed that adipocytes secreted leptin could help tumor cells to proliferate, chemo-resistant, and metastasis via activating pro-tumor pathways." (PMID 27863383, 2016).